ABLIM2 (actin binding LIM protein family member 2)
Description:
May act as scaffold protein. May stimulate ABRA activity and ABRA-dependent SRF transcriptional activity.
Synonyms: KIAA1808
Tractability: PROTAC: its protein half-life has been measured.
Gene: Protein-coding gene on chromosome 4 (7,965,310 to 8,158,832, reverse strand). Ensembl gene ENSG00000163995.
Subcellular location: Cytoplasm
Subcellular location (Human Protein Atlas): Mitochondria; Nucleoplasm
Pathways (Reactome):
Developmental Biology: DCC mediated attractive signaling
Gene Ontology:
Molecular function: actin filament binding; actin binding
Biological process: lamellipodium assembly; cytoskeleton organization
Cellular component: actin cytoskeleton; cytoplasm; myofibril
Genetic constraint (gnomAD): Loss-of-function variants: 53 observed, 89.65 expected, observed/expected ratio (o/e) 0.59, 90% interval 0.47 to 0.74. The upper end of that interval is the gene's LOEUF score, 0.74, which puts it in group 3 of 6, group 1 being the genes least tolerant of losing a copy. Missense variants: 835 observed, 856.9 expected, observed/expected ratio (o/e) 0.97, 90% interval 0.92 to 1.03. Synonymous variants: 361 observed, 343.38 expected, observed/expected ratio (o/e) 1.05, 90% interval 0.96 to 1.15.
Homologues: Orthologues: chimpanzee ABLIM2 (96% identical), rat Ablim2 (91% identical), pig ABLIM2 (89% identical), guinea pig ABLIM2 (89% identical), mouse Ablim2 (86% identical), macaque ABLIM2 (85% identical), dog ABLIM2 (83% identical), tropical clawed frog ablim2 (74% identical), zebrafish ablim2 (66% identical), Drosophila melanogaster Unc-115a (33% identical), Drosophila melanogaster Unc-115b (32% identical). Paralogues in human: ABLIM1 (55% identical), ABLIM3 (52% identical), DMTN (20% identical).
Diseases named in the same sentence as ABLIM2 in open-access papers:
ABLIM2 is named in the same sentence as 7 diseases in open-access papers, as found by Europe PMC text mining. Sharing a sentence is not in itself a finding about the gene and the disease. The quoted sentences say what the papers report.
epilepsy (1 paper, 2021). A brain disorder characterized by episodes of abnormally increased neuronal discharge resulting in transient episodes of sensory or motor neurological dysfunction, or psychic dysfunction. "Although the involvement of the ABLIM2 gene in epilepsy has never been previously reported, it has been associated with neuron guidance processes." (PMID 34722763, 2021).
lung carcinoma (1 paper, 2015). "Consistent with in vitro metastatic cells, the levels of miR-95-3p, pri-miR-95, and ABLIM2 mRNA were decreased in brain metastatic tissues compared with lung cancer tissues and higher cyclin D1 expression was involved in poor prognosis." (PMID 25971210, 2015). "We also found that the levels of miR-95-3p and its host gene, actin binding LIM protein family member 2 (ABLIM2), are lower in brain metastatic lesions than in primary lung cancer, and cyclin D1 expression correlated with poor prognosis." (PMID 25971210, 2015). "Furthermore, ABLIM2 was also decreased in brain metastatic lesions relative to primary lung cancer tissues." (PMID 25971210, 2015).
postmenopausal osteoporosis (1 paper, 2020). Metabolic disorder associated with fractures of the femoral neck, vertebrae, and distal forearm. "Clinical evidence shows that the methylation state of CpG sites of zinc finger protein 267 (ZNF267), actin binding LIM protein family member 2 (ABLIM2), Ras homolog family member J (RHOJ), and cyclin dependent kinase like 5 (CDKL5) genes is correlated with postmenopausal osteoporosis." (PMID 32664681, 2020).
pulmonary embolism (1 paper, 2025). The obstruction of the pulmonary artery or one of its branches by an embolus, sometimes associated with infarction of the lung. "In addition to being associated with BRD, ABLIM2 is associated with increased bleeding risks in humans experiencing pulmonary embolisms and is downregulated in people infected with respiratory syncytial virus." (PMID 40725399, 2025).
cancer (1 paper, 2024). A tumor composed of atypical neoplastic, often pleomorphic cells that invade other tissues. "Among them, ephrin receptor EPHA4, actin binding LIM-proteins ABLIM1 and ABLIM2, semaphorin SEMA7A and glial neurotrophic factor GFRA2 genes, which are involved in axon guidance, are commonly repressed in cancer cells by DiPRO1 and SIX1." (PMID 39009887, 2024).
neurodegenerative disease (1 paper, 2021). A disorder of the central nervous system characterized by gradual and progressive loss of neural tissue and neurologic function. "Furthermore, bioinformatics analyzes have shown that ABLIM2 is a hub gene and plays an important role in neurodegenerative diseases." (PMID 34722763, 2021).
ABLIM2 also shares sentences with these, for which no sentence is quoted: osteoporosis (1 paper).